MIR197 (microRNA 197)
Synonyms: hsa-mir-197; MIRN197; miR-197; miRNA197
Gene: MicroRNA gene on chromosome 1 (109,598,893 to 109,598,967, forward strand). Ensembl gene ENSG00000284443.
Gene Ontology:
Cellular component: RISC complex
Homologues: Orthologues: chimpanzee ptr-mir-197 (100% identical), macaque MIR197 (100% identical), rabbit MIR197 (79% identical).